PIK3CA (phosphatidylinositol-4,5-bisphosphate 3-kinase catalytic subunit alpha)
Diseases named in the same sentence as PIK3CA in open-access papers (continued):
Sharing a sentence is not in itself a finding about the gene and the disease.
endometriosis (73 papers, 2013 to 2025). The growth of functional endometrial tissue in anatomic sites outside the uterine body. "Among the 40 mapped genes in genome-wide association studies, the most common mutations were identified in the protooncogenes KRAS and PIK3CA, as well as in deeply infiltrating endometriosis in KRAS and the suppressor PTEN." (PMID 40647174, 2025). "PIK3CA mutations are frequently seen in ovarian clear-cell carcinoma and endometrioid ovarian cancer associated with endometriosis." (PMID 40076468, 2025). "Research should also focus on efficacy of targeted therapies based on ARID1A and PIK3CA mutations for endometriosis-associated OCCC." (PMID 41244554, 2025). "CCC, with its glycogen-rich, clear cytoplasm, has a poor prognosis even when caught early, is sometimes connected to endometriosis, and frequently shows mutations in PIK3CA, ARID1A, and PPP2R1A." (PMID 41375063, 2025). "Clear cell carcinomas frequently present with variants in ARID1A and PIK3CA, which have been found in adjacent endometriosis variants." (PMID 38132375, 2023). "Another possibility is that the common cancer-related gene mutations found in endometriosis and endometrial epithelium are PIK3CA and KRAS, which are presumed to reflect a multistep carcinogenesis model in many cases." (PMID 38067342, 2023). "In fact, we observed that endometriosis was more frequent in the presence of PIK3CA mutations and that both were associated with diagnosis at the initial stage." (PMID 37400764, 2023). "PIK3CA mutations are also observed in both endometriosis and endometriosis-associated ovarian cancer, such as ovarian clear-cell carcinoma, conditions thought to be derived from abnormal endometrial epithelium." (PMID 37170094, 2023). "All of the 6 PIK3CA-mutation-positive typical endometriosis (TE) were immunohistochemically ARID1A deficient; at the same time, all of the 6 AE harboring PIK3CA mutations were ARID1A deficient." (PMID 35457244, 2022). "We report an extragonadal endometriosis case controlled by drug therapy for 14 years with analysis of the sex hormone receptor expression and PIK3CA mutation." (PMID 33743689, 2021). "Somatic mutations such as ARID1A, PTEN, and PIK3CA have been reported in patients displaying atypical endometriosis and development of endometrioid and clear cell carcinomas." (PMID 34454550, 2021). "In vitro assays showed that migration, invasion, and proliferation were significantly increased in KRAS and PIK3CA mutant cell lines, indicating that these mutations played causative roles in the aggressive behavior of endometriosis." (PMID 34202354, 2021). "Endometriosis-harboring cancer-associated somatic mutations of PIK3CA and KRAS provides new opportunities for studying the multistep processes responsible for the functional and molecular changes in this disease." (PMID 34202354, 2021). "Among the targeted genes, KRAS and PIK3CA are most frequently mutated in the normal epithelial cells of the uterine endometrium and in endometriosis, with a higher mutant allele frequency (MAF)." (PMID 34202354, 2021). "Recently, it has been reported that cancer-associated gene mutations, such as those in KRAS and PIK3CA, are present in cases of endometriosis and adenomyosis, which are benign endometrium-related diseases." (PMID 34442357, 2021). "Recent reports have revealed frequent KRAS and PIK3CA mutations in NE, i.e., in uterine endometrium that are histologically normal and unaffected by endometriosis or adenomyosis." (PMID 31857578, 2019). "Accordingly, the exact contribution of KRAS and PIK3CA mutations to endometriosis remains unresolved." (PMID 31857578, 2019). "On the other hand, it has also to be answered if an early loss of ARID1A expression and/or PIK3CA mutation represents an increased probability for developing OCCC or EnOC in endometriosis." (PMID 24036443, 2013).
endometriosis (continued). "For instance, drugs targeting PIK3CA or MEK signals, such as alpelisib or trametinib, respectively, may theoretically offer a new treatment for women with endometriosis whose lesions have mutations in PIK3CA or KRAS." (PMID 36979957, 2023). "Recent comprehensive analyses have shown that pathological mutations in cancer-related genes such as KRAS and PIK3CA are frequently observed in endometriosis, and these oncogenic abnormalities may lead to high expression of TF and IL6 in endometriosis." (PMID 35565252, 2022). "Additionally, PIK3CA or KRAS mutated clones arising in the histologically normal uterine endometrium have been proposed as the cellular origins of endometriosis." (PMID 34202354, 2021). "In endometriosis-associated clear cell and endometrioid ovarian cancer, miR-381 via targeting PIK3CA could regulate cell motility, growth, and colony formation." (PMID 32850438, 2020). "Similarly, anatomical subtypes of endometriosis, such as ovarian endometrioma (EN-OV) and deep infiltrating (EN-DI) endometriosis, harbor mutations in PIK3CA, ARID1A, PPP2R1A, and/or KRAS20,21." (PMID 31857578, 2019). "Furthermore, PIK3CA may be involved in encouraging the glycolysis of endometriosis, because it is one of the cancer-like mutations discovered in endometriotic tissue." (PMID 40573210, 2025). "Therefore, these PIK3CA mutations may have significant functional relevance and could represent the first step in the progression of endometriosis-associated cancer." (PMID 39768828, 2024). "OCCC is frequently linked to endometriosis and characterized by mutations in ARID1A and PIK3CA, hyperactivation of the PI3K/Akt/mTOR pathway, and overexpression of VEGF, HIF-1α, and IL-6." (PMID 41383608, 2025). "OCCC is characterized by distinct clinicopathological features and molecular alterations, frequently harboring somatic mutations in ARID1A, PIK3CA, and the TERT promoter (TERTp), often in association with endometriosis." (PMID 40862791, 2025). "For example, one recent study found that 79% (19 out of 24) of women with endometriosis exhibited mutations in genes such as ARID1A, KRAS, and PIK3CA within the epithelial cells of the endometriotic lesions analyzed." (PMID 40227624, 2025). "Evidence indicates that 79% (19/24) of patients with endometriosis have mutations in ARID1A, KRAS, and PIK3CA in the epithelial tissue of endometriotic lesions." (PMID 40860812, 2025). "EC, often found at stage I, has a good prognosis, is linked to endometriosis, and commonly involves mutations in CTNNB1, PIK3CA, ARID1A, and PTEN." (PMID 41375063, 2025). "CCC is believed to originate from endometriosis, but ARID1A or PIK3CA mutations have been found in benign endometriosis and even in normal uterine endometrial glands." (PMID 40459063, 2025). "In particular, KRAS, PIK3CA, and ARID1 mutations are frequently discovered in histologically benign endometriotic epithelia and are thought to occur early in endometriosis development." (PMID 39062866, 2024). "Although endometriosis is a benign disease, it is associated with cancer-related gene mutations, such as KRAS or PIK3CA." (PMID 38666954, 2024). "Endometriosis itself is a benign disease; however, it has been reported that endometriosis has KRAS, PIK3CA, or other cancer-associated mutations." (PMID 38666954, 2024). "Recently, our genomic analysis of endometriosis and normal endometrium revealed the presence of somatic mutations in cancer-associated genes such as KRAS and PIK3CA in endometriotic and normal endometrial epithelial cells." (PMID 38067342, 2023). "Exome sequencing of lesions from deep infiltrating endometriosis shows somatic variants in oncogenic driver genes such as ARID1A, PIK3CA, KRAS, or PP2R1A." (PMID 38132375, 2023).
endometriosis (continued). "Endometrioid adenocarcinoma arising from endometriosis shows loss of function of PTEN (21%), KRAS (20%), β-catenin (25%), and PIK3CA (46%)." (PMID 37891997, 2023). "Gene alterations found in both endometriosis and clear-cell ovarian carcinoma include genes such as PIK3CA, PTEN, ERBB2, KRAS, ARID1A, PPP2R1A, MLH1, and CTNNB1." (PMID 35563789, 2022). "Microarray gene-expression analysis revealed several genes that demonstrated correlations with KRAS or PIK3CA invasion-specific gene signatures, which played essential roles in activating the endometriosis progression pathways." (PMID 34202354, 2021). "Known somatic cancer-driver mutations in ARID1A, PIK3CA, and KRAS have been identified in deep endometriosis, indicating that endometriosis is a neoplastic disease." (PMID 34067626, 2021). "Whole-exome sequencing has explored that 79% of patients with deep-infiltrating endometriosis had some harboring oncogenic driver mutations, such as ARID1A, KRAS, PIK3CA, and PPP2R1A." (PMID 34444500, 2021). "Recent research suggest that many putative driver genes and aberrant pathways including ARID1A mutations, PIK3CA mutations, MET activation, HNF-1β activation, and miRNAs dysfunction, play crucial roles in the malignant transformation of endometriosis to OCCC." (PMID 34659566, 2021). "In our analysis of LCM samples, the high MAF of PIK3CA in the tumor of OCCC and endometriosis associated with OCCC suggested clonal expansion in these samples." (PMID 34172890, 2021). "Silencing LOX and PTX3 expression using small molecules is a potential treatment strategy for reducing cell migration, invasion, and proliferation, especially in deep infiltrating endometriosis with KRAS and PIK3CA mutations." (PMID 34202354, 2021). "In the current study, we aimed to comprehensively analyze the roles of KRAS and PIK3CA oncogenes in endometriosis." (PMID 34202354, 2021). "We have reported a variety of molecular events such as ARID1A mutations, PIK3CA mutations, MET activation, HNF-1β activation, and miRNA dysfunction in endometriosis-associated OCCC." (PMID 34659566, 2021). "Consistent with published data, samples of co-occurring endometriosis in some of our adenomyosis patients bore both KRAS and PIK3CA mutations, whereas most co-occurring leiomyoma samples harbored MED12 mutations." (PMID 31857578, 2019). "Endometrioid carcinoma and clear cell carcinoma are caused by endometriosis or endometriosis-related ovarian neoplasms, and these often have ARID1A and PIK3CA mutations." (PMID 31623180, 2019). "This study clearly demonstrated described mutations in contiguous endometriosis shared by EAOC, and even some distant lesions contained the same (PIK3CA and ARID1A) mutations." (PMID 29456620, 2018). "Mutations in ARID1A, PIK3CA, and PTEN may drive the progression from benign endometriosis to cancer." (PMID 40508002, 2025). "Further common driver mutations in endometriosis include ARID1A, PIK3CA, and PPP2R1A." (PMID 38673891, 2024). "PTEN loss may be an early event in cancer development from endometriosis, as well as genetic mutations affecting ARID1A and PIK3CA seem to play a role." (PMID 38438776, 2024). "Moreover, different types of gene-based biomarkers such as ARID1A, PIK3CA, KRAS and CTNNB1 are recurrently mutated in endometrial cancer type I, endometriosis and endometriosis-associated ovarian tumors." (PMID 37189525, 2023). "Interestingly, ovarian tumor cells associated with endometriosis present similar mutations in KRAS, ARID1A, and PIK3CA (a subunit of a kinase involved in tumorigenesis)." (PMID 36979957, 2023).
endometriosis (continued). "In fact, these have mutations in common with endometriosis, such as PTEN, PIK3CA, KRAS and ARID1A." (PMID 37189525, 2023). "Furthermore, ovarian endometrioid cancer shares similar gene alterations with endometriosis, including PIK3CA, PTEN, KRAS, and ARID1A." (PMID 35563789, 2022). "For comparison with the 14 OCCC cases with PIK3CA mutation in the tumor, we obtained FFPE samples of tumor and eutopic endometrium from 12 OCCC cases without PIK3CA mutation in the tumor, 5 HGSOC cases that were unrelated to endometriosis, and 6 EC cases." (PMID 34172890, 2021). "For instance, drugs that target PIK3CA or MEK signals, such as alpelisib or trametinib, respectively, may theoretically offer new options for women suffering with endometriosis, which harbors mutations in PIK3CA or KRAS." (PMID 32066498, 2020). "Ideally, the status of KRAS- and/or PIK3CA-mutated clones in histologically normal endometrium (NE) should be compared between individuals with and without endometriosis." (PMID 31857578, 2019). "Furthermore, endometrium samples from individuals who have undergone endometrial biopsy for a reason unrelated to endometriosis have frequently shown KRAS and PIK3CA mutations." (PMID 31857578, 2019). "Potential oncogenic mutations found included PIK3CA, KRAS, PIK3R1, and FGFR2 in benign epithelial endometrium from women with uterine fibroids, and ARID1A mutations in endometrial stroma from women with endometriosis." (PMID 31717878, 2019). "Similar deletion of ARID1A alone or with knock-in of Pik3ca mutations showed ovarian surface epithelium hyperplasia but no endometriosis." (PMID 30087267, 2018). "They suggest that KRAS mutation and PIK3CA mutation may not be associated with progesterone resistance in terms of aggressiveness of endometriosis; however, progesterone resistance caused by KRAS mutations may affect pain." (PMID 38666954, 2024). "Furthermore, PIK3CA mutations have been observed at high frequency in normal endometrial epithelial cells without cancer or endometriosis." (PMID 37170094, 2023). "The presence of PIK3CA- or KRAS-mutated clones in histologically normal uterine endometrium in endometriosis but also in patients without endometriosis has also been demonstrated, so the theory of the cellular origin of endometriosis requires further investigation." (PMID 37005590, 2023). "Recurrent mutations, such as KRAS, PIK3CA (phosphatidylinositol-4,5-bisphosphate 3-kinase), PPP2R1A (Protein Phosphatase 2 Scaffold Subunit Alpha), and ARID1A (AT-Rich Interaction Domain 1A), are observed in endometriosis and adenomyosis, which suggests similar disease development." (PMID 35206475, 2022). "There is a review report that driver mutations in endometriosis are not necessarily synonymous with malignancy or precancerous lesions, and in light of this, the PIK3CA mutation observed in this case may be a passenger mutation rather than a driver mutation." (PMID 33743689, 2021). "Moreover, atypical endometriosis and EAOC may share several molecular alterations such as ARID1A and PIK3CA mutations, PTEN loss, MET amplifications, and HNF1B overexpression, suggesting a common molecular mechanism for malignant development." (PMID 27992377, 2017). "Next-generation sequencing (NGS) has shown that endometriosis and adenomyosis involve genetic alterations such as KRAS, PIK3CA, PPP2R1A and ARID1A." (PMID 37296736, 2023). "The identification of AKT1, or more generally, genes in the PI3K/AKT/mTOR pathway (including MTOR, PIK3CA, and PIK3R1 in addition to ATK1), is in line with current interests targeting this pathway in endometriosis." (PMID 35401535, 2022). "Microarray analysis was also helpful to identify the pathways regulated in endometriosis in the HMOsisEC10 KRAS and HMOsisEC10 PIK3CA mutant cells." (PMID 34202354, 2021). "Thus, endometrial clones bearing KRAS and/or PIK3CA mutations may not necessarily drive the pathogenesis of endometriosis." (PMID 31857578, 2019).
endometriosis (continued). "In the first case, we identified de novo activating mutations in PIK3CA and KRAS in endometrioid cancer lesions but not in endometriosis." (PMID 35359373, 2022). "LtfCre0/+; (Gt)R26Pik3ca*H1047R; Arid1afl/fl mice (henceforth, PIK3CA/ARID1A mutant mice) develop endometrial hyperplasia and myometrial invasion with features of endometrioid carcinoma, which can also develop an endometriosis phenotype following uterotubal incision surgery." (PMID 36424602, 2022). "In the first case, we identified de novo activating PIK3CA and KRAS mutations in endometrioid cancer lesions but not in endometriosis." (PMID 35359373, 2022). "In general, both endometrioid and clear cell ovarian cancer with or without endometriosis have common high frequency mutations in ARID1A, PIK3CA, catenin betat 1 (CTNNB1), PTEN, and KRAS." (PMID 30087267, 2018). "Thus, inhibition of KRAS/PIK3CA, or their downstream targets such as LOX or PTX3 inhibitors, might be clinically effective in progestin-resistant endometriosis-related pain." (PMID 38666954, 2024). "Interestingly, somatic driven mutations in KRAS, PTEN, PIK3CA and ARID1A have been also observed in more than 26% of cases of deep infiltrating endometriosis lesions, which are associated with virtually no risk of malignant transformation." (PMID 35457244, 2022). "Furthermore, one study showed that recurrently mutated cancer driver genes, such as KRAS, PIK3CA, PPP2R1A, and ARID1A, are also present in endometriosis without cancer association." (PMID 34202354, 2021). "For example, some known somatic driver mutations in the genes ARID1A, PIK3CA, KRAS, and PPP2R1A have been found in the endometriotic lesions of 19 of 24 patients with deep-infiltrating endometriosis even though this form of endometriosis almost never undergoes malignant transformation." (PMID 29945886, 2018). "These authors analyzed the PIK3CA gene at exons 9 and 20 in a total of 23 CCA cases, with synchronous putative precursor lesions; each case showed endometriosis that was contiguous with carcinoma with or without cytological atypia." (PMID 40364006, 2025).